IL10 (interleukin 10)
Diseases named in the same sentence as IL10 in open-access papers (continued):
Sharing a sentence is not in itself a finding about the gene and the disease.
tumor (continued). "Immune‐related analysis revealed that effector T cells (CD8+CD3+) recruitment, immunostimulation cytokine rise (IL‐12), and immunosuppressive cytokine decrease (IL‐10) in the distant tumors are responsible for the distant tumor recession." (PMID 36156442, 2022). "In experimental mouse models, infiltrating B cells exert a negative prognostic influence, probably due to their ability to produce IL-10 and IgG, which can activate the M2 pro-tumour phenotype in macrophages and promote early stages of carcinogenesis." (PMID 35954497, 2022). "Correspondingly, the immunosuppressive cytokine IL-10 showed a significant increase in expression through progression, and this correlated with greater numbers of putatively tumor-promoting neutrophils (elastase) and macrophages (CD68)." (PMID 35379804, 2022). "In fact, in this study, NEO specifically reduced IL-10 production by circulating and tumor-infiltrating Tregs, suggesting a reduced suppressive capacity." (PMID 36509285, 2022). "TAM are activated by mediators secreted from tumor-infiltrating lymphocytes such as Th2, Treg cells, IL-10, TGF-β." (PMID 35183252, 2022). "PD-L1 (p = 0.001, FC = −5.7) and IL10 (p = 0.009, FC = −1.3) expression was significantly lower in the T3/T4 tumor group." (PMID 35406584, 2022). "The pro-tumor cells are considered immunoregulatory cells that produce anti-inflammatory cytokines (e.g IL-10 and TGF-b)." (PMID 35742884, 2022). "IL-10, a kind of immunosuppressive cytokines, was produced at high levels in tumor-bearing states to restrain the function of antitumor effector T cells." (PMID 36035394, 2022). "M2 TAMs mediate tumor immunosuppression through the secretion of immunosuppressive cytokines such as IL-1β, IL-6, IL-10, and TGF-β and suppress T cell immune responses through the expression of the immunosuppressive ligand PD-L1." (PMID 36092724, 2022). "In cHL patients, IL-10 is also regarded as a marker of tumor burden and as an unfavorable host-tumor factor." (PMID 35875135, 2022). "IL-10 promotes tumor immune surveillance escape and IL-8 is a key mediator of angiogenesis, tumorigenicity, and metastasis." (PMID 35955737, 2022). "Concentration of pro‐inflammatory and pro‐angiogenic cytokines including IL‐1a, IL‐2, IL‐6, IL‐10, IL‐12, and IL‐17A, in peripheral blood of tumor bearing mice receiving anti‐MUC1 nanobody was significantly lower compared to the PBS receiving group." (PMID 34694686, 2022). "Our results indicated the inefficient impact of IL-10 on the therapy outcomes regarding the tumor size." (PMID 35752792, 2022). "In particular, interleukin-10 (IL-10), derived from TAMs, induces the accumulation of regulatory T cells (Tregs) that contribute to tumor aggressiveness." (PMID 35955576, 2022). "Th2 cells, which primarily secrete IL-2 and IL-10, have been shown to promote immunosuppression, and tumor progression and metastasis." (PMID 36276933, 2022). "Tumor-derived exosomes modulate immune cells within the TME to secrete large quantities of IL-10 to assist tumor cells to evade immune surveillance." (PMID 36233088, 2022). "Hypoxia tumor-derived exosomal-hsa-circ-0048117 is transmitted to macrophages to promote their polarization to M2 macrophages, which enhance the invasive and migratory ability of tumor cells through secreting IL-10, Arg1, and TGF-β." (PMID 36233088, 2022). "Then the levels of IFN-γ, IL-10 and caspase-9, and also the tumor size in mice receiving anti-IL-10-added vaccines were compared with those of mice treated with isotype homologs six weeks after tumor challenge." (PMID 35752792, 2022).
tumor (continued). "In our study, the mRNA levels of IL-6 and IL-8 were decreased in the GC group, probably due to the elevated IL-10 level in the local area of the tumor." (PMID 35572666, 2022). "On the contrary, mast cells, through the release of IL-8 and IL-10, promote the expansion of tumor mass." (PMID 36430483, 2022). "IL-10, which is known to have tumour promoting effects, has been also increased in the serum of tumour-bearing mice after SID treatment." (PMID 36010845, 2022). "M2 macrophages have pro-tumor effects and promote tumor growth and immune evasion by inducing angiogenesis and producing anti-inflammatory cytokines such as IL-3, IL-10, and TGF-β11–13." (PMID 35136176, 2022). "A major example is represented by protumorigenic M2-TAMs, which express multiple immunosuppressive (e.g., prostaglandin E2, IL10) and tumor-promoting factors leading to suppressed anti-tumor responses." (PMID 36365207, 2022). "Continuous activation of STAT3 in tumor-associated immune cells activates the expression of downstream genes VEGF, IL-10 and IL-6, and causes the proliferation of tumor-infiltrating hematopoietic stem cells, which ultimately leads to poor prognosis." (PMID 36561336, 2022). "A specific MDSC subset (CD14pos HLA-DRneg/low) found in the tumor tissue and peripheral blood of patients with HCC is characterized by the production of IL-10 and TGF-β, which induce Tregs and are associated with tumor progression." (PMID 35216137, 2022). "IL-10 secreted by Breg cells attenuated the activation of T cells and NK cells to promote tumor progression." (PMID 35563678, 2022). "Mast cells release tumor-promoting cytokines, such as IL10 and TGF-β1, and pro-angiogenic factors and proteases that enhance fibroblast proliferation, suggesting their importance in favoring tumorigenesis." (PMID 35267668, 2022). "Pearson correlation analysis further showed that OPN was positively associated with M2 macrophage markers (CD163, VSIG4, MS4A4A, CX3CR1, and MRC1) and tumor-associated macrophage (TAM) markers (CCL2, CD68, and IL10)." (PMID 35669197, 2022). "Immune genes previously linked to a suppressive tumor microenvironment in WTs (TGFB1, IL10) are highly expressed in all EX2 tumors whilst activating genes (TNF, IL6) show a more restricted expression pattern." (PMID 36230794, 2022). "CD39+CD103+ tumor-resident memory T cells sorted from human high-grade EC differentially expressed IL-2, IL-10, IL-13, IL-17A, IL-21, and IL-22 before and after activation." (PMID 36531027, 2022). "In the tumor microenvironment, mTOR signaling regulates the activity of macrophages and T-cells through inflammatory factors like IL-10, TGF-beta, and membrane bound CTLA-4 and PD-1." (PMID 36304922, 2022). "Large amounts of Tregs accumulated locally in tumors, and the TIM-3 signal pathway can regulate Tregs immuno-suppressive function by secreting inhibitory cytokines such as transforming growth factor-β and IL10 to promote tumor immune escape." (PMID 36081997, 2022). "In contrast, M2 macrophages that are responsive to Th2-related cytokines and have high expression levels of IL-10 are immunosuppressive and in favor of tumor promotion." (PMID 36173644, 2022). "IL-10 inhibits the anti-tumor immune reaction, suppressing cytotoxic T cell functions by immune-suppressive (CD4+CD25+) Treg cells." (PMID 35955576, 2022). "Cytokines released by tumor cells, such as IL-10 and IFN-β, can manipulate the immunological functions of astrocytes by inducing the anti-inflammatory astrocytic phenotype." (PMID 35205842, 2022). "IL-10 is also an immunomodulatory cytokine that exhibits both pro- and antitumor characteristics, depending on the tumor microenvironment, showing its behavior in the pathogenesis and progression of CRC." (PMID 36296636, 2022). "The suppression of inflammatory-related cytokines (IL-6 and IL-10) can inhibit tumor cell proliferation and metastasis via immunosuppression." (PMID 35630704, 2022).
tumor (continued). "Parallel to the analysis of BCRP expression, the changes in the levels of IL-1β, TNF-α, and IL-10 cytokines in peripheral blood in the control and tumor-bearing animals were investigated." (PMID 35053477, 2022). "When the pathway is activated, TAM will be polarized to M2 phenotype and release IL10, aiming to promote the progression of tumor." (PMID 35186730, 2022). "In contrast, tumor microenvironment-educated macrophages release IL-10 and TGF and inhibit the activation of CTLs and NK cells at advanced stages of tumor development." (PMID 36207500, 2022). "Although there are many cytokines and chemokines secreted in the GBM microenvironment, IL-10 is thought to be a key immunosuppressive cytokine and is found in high quantities in various neoplasms and primarily secreted by macrophages, as well as GBM cells." (PMID 35203636, 2022). "A meta-analysis revealed that the serum levels of IL-10 are positively correlated with tumor progression, showing the importance of TAMs in the promotion of tumor development." (PMID 35634292, 2022). "Altogether, Breg cells suppress anti-tumor immunity via the secretion of anti-inflammatory cytokines such as IL-10, TGF-β and IL-35." (PMID 36033455, 2022). "The expression of FOXP3 and IL-10 mRNA was obviously decreased in the tumor-bearing mice of the treatment group, while the secretion of IL-12 was increased and the contents of IL-10 and TGF-β were decreased." (PMID 36235242, 2022). "ProcartaPlex cytokine ELISA analysis indeed revealed that IL-10 was significantly reduced in the supernatant of Δ/Δ Pdgfrb tumor cells cultured in vitro, as were transcript levels of IL-10." (PMID 36045346, 2022). "Enzyme immunoassay analysis showed decreased TNFα in tumors in the distal part of the colon and increased IL10 in proximal tumors and in non-tumor tissues." (PMID 36555251, 2022). "Tumor cells in the hypoxic niche not only produce cytokines including IL-6, IL-10 and TGF-β, but also upregulate pro-angiogenic factors (VEGF, PDGF-β or EPO) that recruit pericytes and trigger neoangiogenesis." (PMID 35769460, 2022). "The current study also examined the impact of IL-10 on tumor regression induced by E7&IL-24, E7, or IL-24 in parallel with our main study by following up the tumor volume for up to six weeks." (PMID 35752792, 2022). "IL-10 has been widely accepted to be an immunosuppressive cytokine in cancer, as it plays important roles in the promotion of tumor immune escape." (PMID 34623465, 2022). "Both tumor cells and melanoma-associated fibroblasts (MAFs) produce COX-2 and IDO, inducing the expression of IL-10 in macrophages." (PMID 36713558, 2022). "In this study, we reported that CXCL14 was highly expressed in PC tumor tissues and positively correlated with expressions of PD-L1 and IL-10, as well as pathological stages." (PMID 35669852, 2022). "In the pre-metastatic niche, NK cells can be part of tumor-infiltrating leukocytes before CTCs seeding; in metastatic lesions, NK cells can be suppressed by IL-10, TGF-β, and adenosine, leading to increased tumor growth." (PMID 36294305, 2022). "As a result, tumor cells release the immunosuppressive cytokine IL-10 and regulatory T cells are activated in the tumor microenvironment, which suppress the antitumor immunity." (PMID 36258234, 2022). "Eosinophils that infiltrate into tumor environment play both antitumorigenic roles and pro-tumorigenic roles, as they can release interleukins (like IL-10, IL-12 and IFN-γ) or chemokines and growth factors (like EGF, FGF and TGF-β)." (PMID 35903153, 2022). "In contrast, exosomes from HNSCC cells also stimulate the expression of IL-10 in macrophages and PD-L1 in tumor cells, which eventually forms an immunosuppressive environment." (PMID 35740551, 2022). "Tumour‐associated macrophages (TAM) mainly have M2 polarisation and produce immunosuppressive cytokines such as IL10, TGFB and PGE2 and low levels of inflammatory cytokines (IL12, IL1B, TNF and IL6)." (PMID 35445563, 2022).
tumor (continued). "In creating a more immunosuppressive environment, GSCs have been seen to inhibit T cell proliferation and cytotoxic T cell activation, as well as secrete factors such as IL-10 and TGFβ, which suppress the tumor-killing function of macrophages." (PMID 36338705, 2022). "The frequencies of CD4+IL-4+, CD4+IL-17+ and CD8+IL-10+ showed significant increases in laryngeal SCC patients with tumor size ≤ 3 cm (P = 0.024, P = 0.048, P = 0.001, respectively)." (PMID 36376825, 2022). "These EV-mediated effects were dependent on TGFβ-1 and IL-10, as neutralising antibodies specific for these cytokines blocked the ability of tumor-derived EVs to expand Treg cells." (PMID 35563789, 2022). "Tumor hypoxic stress causes HIF-1α to mediate the secretion of a variety of immune evasion-promoting molecules from tumor cells, including TGF-β, VEGF, IL-10, and PGE2." (PMID 36233088, 2022). "Usually, activated cytotoxic T lymphocytes (CTLs) can attack cancer cells to suppress tumor growth, while TAMs express immunosuppressive cytokines, chemokines, and growth factors like IL10 and TGFB1 to make CTLs hyporesponsive." (PMID 36211379, 2022). "IL-10 is an important immunosuppressive factor released by tumor cells during the progression of malignancies." (PMID 35178106, 2022). "According to our data, the T-cell polarization ability of DCs altered by different tumor cell lines promotes the development of IFNγ or IL-10-producing T cells, but different tumors induce diverse responses." (PMID 36194602, 2022). "The Q-PCR results from all the tumors of each treatment group showed that several chemokines and cytokines were positively correlated with tumor size, including IL-4a, IL-6, IL-10, CSF-1, CSF-2, INF-r, and NOS-2." (PMID 35058524, 2022). "When IL-10 induces M2 macrophages polarization to promote tumor immune escape during tumor progression, IL-35 secreted from Tregs induces non-Tregs that inhibit other cells by the “infectious tolerance” mechanism." (PMID 35371055, 2022). "On the contrary, IL-32γ isoform is shown to diminish the levels of cytokines that promote tumor growth such as TNF-α, IL-1β, and IL-6, whereas the levels of IL-10 cytokine, a tumor growth-inhibiting cytokine, were elevated." (PMID 35281008, 2022). "With FOXP3 knockout, tumor cells secreted less IL-10 and TGF-β1, and T-cell survival was significantly upregulated, suggesting that FOXP3 plays an important role in malignant phenotypes, particularly during invasion and immune escape." (PMID 36185217, 2022). "IL-35 has been shown to act together with IL-10 in TME to induce BLIMP-1 mediated upregulation of inhibitory receptors on tumor-reactive CD4+ and CD8+ T cells." (PMID 36248808, 2022). "Many studies have attempted to improve low dose IL-2 therapeutic effect by depleting regulatory T cells, or neutralizing TGF-β or IL-10 with significant, but minor, increases in the anti-tumor response." (PMID 36231109, 2022). "Local signals IL-13, IL-6, and IL-10 in the tumor microenvironment were reported to polarize macrophages into protumoral M2-like cells, which was in line with the results of flow cytometry." (PMID 35154567, 2022). "After superantigenic stimulation of SEs, Treg cells lose their immunosuppressive activity, and a Treg induces Th2 proliferation and the secretion of IL-10 to aggravate the skin inflammatory response." (PMID 35878202, 2022). "For the CAR-T20 groups, the tumors were largely diminished at 14 days post-administration, and the levels of human IFN-γ and IL-10 in the tumor-bearing mice were also significantly reduced." (PMID 36352168, 2022). "In a recent study, authors found a significant expression of IL-10 in tumor-infiltrating B-cells of TNBC patients, driving isotype switch to the IgG4 isotype in an IL-10 dependent manner." (PMID 35681689, 2022). "Type I NK T-cells, also called invariant NK T-cells, mediated the secretion of IFN-γ and TNF-α that improves antitumor effect and IL-4, IL-10, and IL-13 modulating tumor niche." (PMID 36569859, 2022).
tumor (continued). "In comparison, IL10 was different only in the proximal part of the colon, where it was higher in tumors and non-tumor tissues compared to the control." (PMID 36555251, 2022). "On the one hand, plasma cells can inhibit the activity of effector T cells by releasing immunosuppressive cytokines such as IL-10 and IL-35, thereby weakening the tumor-killing effect of effector T cells." (PMID 36569837, 2022). "Inflammatory cytokines within the tumor microenvironment, such as interleukin (IL)-2, IL-6, IL-10, IFNs and tumor necrosis factor α, have also been shown to induce B7-H4 expression on both tumor cells and monocytes/macrophages." (PMID 34275008, 2022). "Another study revealed that TIGIT causes polarisation of CD155-expressing type 1 proinflammatory macrophages into IL-10-secreting type 2 macrophages (which are tumour-promoting) in mice." (PMID 35328510, 2022). "Conversely IL-4, IL-10 and IL-13 secreted by tumor or stromal cells can stimulate conversion of M0 to pro-tumor M2 macrophages." (PMID 36253762, 2022). "A study revealed that TAMs infiltrating TNBCs secrete IL-10, which contributes to tumor progression." (PMID 35960749, 2022). "proved that IL-10 is not only a biomarker but also a key cytokine in macrophage polarization that leads to tumor growth and can inhibit effective cutaneous T-cell lymphoma therapy." (PMID 35875135, 2022). "Our study provides evidence for the vital role of IL‐10 induced by EMT tumour cells in the creation of a favourable TME for GC progression through regulating Treg cell differentiation." (PMID 35969010, 2022). "M2 macrophages express numerous anti-inflammatory molecules, including ARG-1, TGF-β, and IL-10, promoting tumor immunosuppression and progression." (PMID 35889289, 2022). "In one study, lower concentrations of ellagic acid decreased IL-1β, IL-6, IL-1Ra, and IL-10 production by PBMC incubated with a tumor cell line (HT-29), whereas higher concentrations inhibited the production of all cytokines examined, except IFN-γ." (PMID 35745713, 2022). "A positive correlation was discovered between IL-10 level and tumor size, which resulted in poor prognosis." (PMID 36140220, 2022). "A remarkably decreased number of FoxP3-expressing and IL-10-producing CD4+ Tregs were observed in the tumors of 4T1+d-MAPPS-treated animals compared to tumor-bearing animals that received saline (p < 0.05)." (PMID 35757015, 2022). "In sum, the incorporation of anti-IL-10 showed promising signs of complementary therapy in combination with cancer immunotherapy for more efficient tumor eradication." (PMID 35752792, 2022). "TAMs exhibiting an M2-like phenotype induce the cancer-cell-mediated secretion of tumor growth factors, cytokines such as IL-10, and proteases, which promote angiogenesis, connective tissue breakdown and tumor-cell proliferation." (PMID 35053451, 2022). "This MR on the TAMs interacts with the STn-positive regions and MUC16 on tumor cells, which leads to the production of the anti-inflammatory cytokine IL-10 and a decrease in the T cell attracting inflammatory chemokine CCL3, facilitating immune suppression." (PMID 36686742, 2022). "While Th2 cells secrete IL-4, IL-5, and IL-10 to promote polarisation of M2 macrophages, the positive interaction between the 2 cells constructs a tumour-suppressive immune microenvironment." (PMID 35591854, 2022). "Various tumor-derived factors within or on TEVs surface induce MDSCs in vitro, including IL-1β, IL-6, IL-10, prostaglandin E2 (PGE2), TGF-β, stem cell factor (SCF), and VEGF." (PMID 36612080, 2022). "IL-10 can create an immunosuppressive tumor microenvironment through multiple pathways including NF-κB, and promote the transformation of cancer stemness." (PMID 35664314, 2022). "Conversely, other studies have suggested that IL-10 is equally likely to enhance anti-tumor immunity." (PMID 35204426, 2022).